CHMP2A (charged multivesicular body protein 2A)
Description:
Probable core component of the endosomal sorting required for transport complex III (ESCRT-III) which is involved in multivesicular bodies (MVBs) formation and sorting of endosomal cargo proteins into MVBs. MVBs contain intraluminal vesicles (ILVs) that are generated by invagination and scission from the limiting membrane of the endosome and mostly are delivered to lysosomes enabling degradation of membrane proteins, such as stimulated growth factor receptors, lysosomal enzymes and lipids. The MVB pathway appears to require the sequential function of ESCRT-O, -I,-II and -III complexes. ESCRT-III proteins mostly dissociate from the invaginating membrane before the ILV is released. The ESCRT machinery also functions in topologically equivalent membrane fission events, such as the terminal stages of cytokinesis. Together with SPAST, the ESCRT-III complex promotes nuclear envelope sealing and mitotic spindle disassembly during late anaphase. Recruited to the reforming nuclear envelope (NE) during anaphase by LEMD2. ESCRT-III proteins are believed to mediate the necessary vesicle extrusion and/or membrane fission activities, possibly in conjunction with the AAA ATPase VPS4. (Microbial infection) The ESCRT machinery functions in topologically equivalent membrane fission events, such as the budding of enveloped viruses (HIV-1 and other lentiviruses). Involved in HIV-1 p6- and p9-dependent virus release.
Synonyms: BC2; CHMP2; BC-2; VPS2; VPS2A
Tractability: Antibody: UniProt places it where antibodies can reach, with high confidence; its Gene Ontology location is reachable by antibodies, with high confidence; the Human Protein Atlas places it where antibodies can reach. PROTAC: UniProt records ubiquitination sites on it; ubiquitination databases record sites on it; its protein half-life has been measured.
Gene: Protein-coding gene on chromosome 19 (58,551,452 to 58,555,128, reverse strand). Ensembl gene ENSG00000130724.
Subcellular location: Late endosome membrane; Nucleus envelope
Subcellular location (Human Protein Atlas): Cytosol; Nucleoplasm; Plasma membrane
Pathways (Reactome):
Disease: Budding and maturation of HIV virion; HCMV Late Events; Translation of Replicase and Assembly of the Replication Transcription Complex
Autophagy: Late endosomal microautophagy; Macroautophagy
Vesicle-mediated transport: Endosomal Sorting Complex Required For Transport (ESCRT); Lysosome Vesicle Biogenesis
Cell Cycle: Sealing of the nuclear envelope (NE) by ESCRT-III
Programmed Cell Death: Pyroptosis
Gene Ontology:
Molecular function: membrane bending activity; phosphatidylcholine binding; protein binding; protein domain specific binding
Biological process: autophagosome maturation; autophagy; establishment of protein localization; exit from mitosis; late endosome to lysosome transport; membrane fission; membrane invagination; midbody abscission; mitotic metaphase chromosome alignment; multivesicular body sorting pathway; negative regulation of centriole elongation; nuclear membrane reassembly; nucleus organization; plasma membrane repair; positive regulation of exosomal secretion; protein homooligomerization; protein polymerization; regulation of centrosome duplication; regulation of mitotic spindle assembly; ubiquitin-dependent protein catabolic process via the multivesicular body sorting pathway; viral budding from plasma membrane; viral budding via host ESCRT complex; viral release from host cell; ESCRT III complex disassembly; late endosome to vacuole transport; and 5 more
Cellular component: amphisome membrane; autophagosome membrane; chromatin; ESCRT III complex; extracellular exosome; kinetochore; kinetochore microtubule; lysosomal membrane; membrane; membrane coat; midbody; multivesicular body membrane; nuclear envelope; nuclear pore; plasma membrane; cytosol; late endosome membrane
Genetic constraint (gnomAD): Loss-of-function variants: 6 observed, 23.3 expected, observed/expected ratio (o/e) 0.26, 90% interval 0.14 to 0.51. The upper end of that interval is the gene's LOEUF score, 0.51, which puts it in group 2 of 6, group 1 being the genes least tolerant of losing a copy. Missense variants: 303 observed, 310.39 expected, observed/expected ratio (o/e) 0.98, 90% interval 0.89 to 1.07. Synonymous variants: 125 observed, 113.54 expected, observed/expected ratio (o/e) 1.1, 90% interval 0.95 to 1.28.
Homologues: Orthologues: chimpanzee CHMP2A (100% identical), macaque CHMP2A (100% identical), guinea pig CHMP2A (99% identical), mouse Chmp2a (99% identical), dog CHMP2A (99% identical), rabbit CHMP2A (99% identical), pig CHMP2A (99% identical), tropical clawed frog chmp2a (90% identical), zebrafish chmp2a (89% identical), Drosophila melanogaster Vps2 (74% identical), Caenorhabditis elegans vps-2 (69% identical). Paralogues in human: CHMP2B (32% identical), CHMP1B (26% identical), CHMP3 (26% identical), CHMP1A (22% identical).
Diseases named in the same sentence as CHMP2A in open-access papers:
CHMP2A is named in the same sentence as 28 diseases in open-access papers, as found by Europe PMC text mining. Sharing a sentence is not in itself a finding about the gene and the disease. The quoted sentences say what the papers report.
glioblastoma (4 papers, 2013 to 2025). The most malignant astrocytic tumor (WHO grade IV). "Some studies regarding ESCRT-III members have demonstrated that CHMP2A sensitized glioblastoma stem cells to death mediated by natural killer cells." (PMID 40558556, 2025). "In another study, the role of CHMP2A in regulating tumor resistance to NK cell-mediated cytotoxicity was explored using a sophisticated “two cell type” whole-genome CRISPR-Cas9 screening system focused on human glioblastoma stem cells (GSC) and OSCC." (PMID 39192980, 2024). "Thus, inhibiting CHMP2A and related pathways, it may be possible to counteract tumor resistance mechanisms and improve the therapeutic outcomes for patients suffering from various forms of cancer, including glioblastoma and head and neck squamous cell carcinoma." (PMID 39192980, 2024).
head and neck squamous cell carcinoma (4 papers, 2024 to 2025). A squamous cell carcinoma that arises from any of the following anatomic sites: lip and oral cavity, nasal cavity, paranasal sinuses, pharynx, larynx, and salivary glands. "Using an immunocompetent mouse model and the syngeneic 4MOSC head and neck squamous cell carcinoma model, CHMP2A was knocked out (KO) via CRISPR/Cas9 in 4MOSC1 cells." (PMID 39192980, 2024). "Recent studies have demonstrated that, in a head and neck squamous cell carcinoma (HNSCC) model, the ablation of the CHMP2A gene precipitates NF-κB activation in neoplastic cells, culminating in augmented chemokine secretion that facilitates NK cells migration towards the tumor microenvironment." (PMID 39493763, 2024).
glioma (3 papers, 2021 to 2022). A benign or malignant brain and spinal cord tumor that arises from glial cells (astrocytes, oligodendrocytes, ependymal cells). "Combining the two databases, we noticed that MVB12A, VPS25, CHMP2A, and IST1 were highly expressed in glioma." (PMID 34863175, 2021). "For instance, MVB12A, VPS25, CHMP2A, and IST1 were significantly upregulated in glioma, whereas VPS36 and CHMP1B were significantly downregulated." (PMID 34863175, 2021).
osteosarcoma (2 papers, 2022 to 2024). A usually aggressive malignant bone-forming mesenchymal neoplasm, predominantly affecting adolescents and young adults. "As an autophagosome regulator, the depletion of chmp2a triggers a caspase-8 cascade, inducing apoptosis in osteosarcoma and neuroblastoma cells." (PMID 39456653, 2024).
prostate carcinoma (2 papers, 2017 to 2022). A carcinoma that arises from epithelial cells of the prostate gland. "The two clusters showed significant differences in the expression of PRGs; CHMP2A, CHMP4C, CYCS, CASP6, CASP8, GPX4, and TIRAP have high expression levels in cluster B, suggesting that these genes may associate with poor prognosis in prostate cancer." (PMID 35813821, 2022).
renal fibrosis (2 papers, 2021 to 2024). A final common manifestation of a wide variety of chronic kidney diseases characterized by glomerulosclerosis and tubulointerstitial fibrosis. "PTEN alleviates renal fibrosis by upregulating phagophore closure mediated by the autophagy-related protein CHMP2A." (PMID 39165377, 2024). "PTEN-mediated CHMP2A could be a novel therapeutic approach for renal fibrosis resulting from AKI progression to CKD." (PMID 39165377, 2024). "Collectively, our study suggests that PTEN relieved renal maladaptive repair in terms of cell damage, apoptosis, and renal fibrosis by upregulating CHMP2A-mediated phagosome closure, suggesting that PTEN/CHMP2A may serve as a novel therapeutic target for the AKI to CKD transition." (PMID 34789720, 2021).
bladder cancer (1 paper, 2023). "Based on these ROC curves, LASPGFPGEYANDQERR3 (=MASP2), TFISPIK2 (=C3), VTAAPQSVCALR2 (=A2M), KTPEELLR2 (=CHMP2A) and SVDPDSPAEASGLR2 (=NHE-RF1) have a high discriminating power between the bladder cancer patients and the healthy control group and might be good biomarker candidates." (PMID 37371512, 2023).
endometriosis (1 paper, 2025). The growth of functional endometrial tissue in anatomic sites outside the uterine body. "Compared to normal human endometriosis cells, the expression of BAK1, CHMP2A, GPX4, and GSDMD was upregulated, whereas the expression of CHMP2B, IRF2, and TIRAP was negatively regulated in UCEC cells." (PMID 40535818, 2025).
lung adenocarcinoma (1 paper, 2023). A carcinoma that arises from the lung and is characterized by the presence of malignant glandular epithelial cells. "Further, we validated the expression level of CHMP2A and NLRC4 in 16 cases of lung adenocarcinoma and matched adjacent cancerous tissues by using qRT-PCR analysis." (PMID 37077542, 2023).
tumor (28 papers, 2003 to 2025). "This modification led to significantly increased NK cell-mediated killing in a xenograft model using immunodeficient mice, confirming the crucial role of CHMP2A in modulating tumor sensitivity to NK cell cytotoxicity." (PMID 39192980, 2024). "CHMP2A was also found to mediate tumor resistance by secreting extracellular vesicles containing ligands like MICA/B and tumor necrosis factor-related apoptosis-inducing ligand (TRAIL) that induce NK cell apoptosis." (PMID 38891890, 2024). "This study not only sheds light on the intricacies of tumor-immune system interactions but also identifies CHMP2A as a promising target for enhancing the efficacy of NK cell-based immunotherapies." (PMID 39192980, 2024). "CHMP2A is an autophagy-related protein 17 that has recently been reported to regulate tumor sensitivity to natural killer cell-mediated cytotoxicity." (PMID 38706914, 2024). "In the OSCC context, specifically within the CAL27 tumor model, it was demonstrated that CHMP2A mediates tumor resistance through a different mechanism-by the secretion of extracellular vesicles (EVs)." (PMID 39192980, 2024). "The investigation revealed that CHMP2A deletion in tumor cells activates the NF-κB pathway, which in turn enhances the secretion of chemokines." (PMID 39192980, 2024). "We observed increased migration of NK cells towards CHMP2A KO tumor cells that showed increased secretion of CXCL10 and CXCL12, chemokines involved in NK cell migration." (PMID 35393416, 2022). "CHMP2A-knockout (KO) tumor cells secrete more CXCL10 and CXCL12, increasing NK cell migration in vitro." (PMID 35393416, 2022). "Flow cytometric analysis of tumor-infiltrating NK cells demonstrates a significant increase of human NK cells in CHMP2A-KO tumors, suggesting that reducing the EVs secretion in the tumor environment can increase the number of tumor-infiltrating NK cells." (PMID 35393416, 2022). "Seven pyroptosis-related genes (ELANE, IL18, CHMP2B, CHMP4C, CASP9, CHMP6, and CHMP2A) were downregulated in tumor tissues, while 31 pyroptosis-related genes were upregulated in tumor tissues." (PMID 35432539, 2022). "Our data demonstrate CHMP2A and tumor secreted EVs can be responsible for inducing apoptosis in NK cells, thus limiting their cytotoxic potential." (PMID 35393416, 2022). "Here based on a genome-wide CRISPR screening, the authors show that expression of CHMP2A confers tumor cell resistance to NK cell-mediated cytotoxicity, mechanistically involving CHMP2A-dependent regulation of extracellular vesicle secretion." (PMID 35393416, 2022). "In the HNSCC model we demonstrate that CHMP2A mediates tumor resistance to NK cells via secretion of extracellular vesicles (EVs) that express MICA/B and TRAIL." (PMID 35393416, 2022). "We show that deletion of CHMP2A activates NF-κB in tumor cells to mediate increased chemokine secretion that promotes NK cell migration towards tumor cells." (PMID 35393416, 2022). "We found that a higher expression of VPS25 and CHMP2A was more frequent in tissues with advanced tumor stage from GEO and TCGA databases." (PMID 34863175, 2021). "Furthermore, CHMP2A has been shown to induce apoptosis in NK cells, thereby reducing their anti-tumor activity through the secretion of EVs expressing MICA/B and TRAIL." (PMID 40149859, 2025). "Ablation of GSDMD reduced the number of tumor cells that harbor aggregated CHMP2A and CHMP4B." (PMID 38898209, 2024). "Chmp2a and tumor-EVs can induce NK cell apoptosis, limiting cytotoxicity." (PMID 39456653, 2024). "The CHMP2A KO in 4MOSC1 cells enhanced NK cell-mediated tumor cell killing in vitro." (PMID 39192980, 2024). "The evaluation of the expression of CHMP2A and characterization of tumor secreted EVs in patients may explain some mechanisms of immune escape and speed the development of new drugs that can target these immune-suppressive processes." (PMID 35393416, 2022).
tumor (continued). "Moreover, since we observe that tumor-derived EVs can inhibit NK cell activity through MICA/B and TRAIL, deletion of CHMP2A limits the secretion of EVs by the tumor cells leading to enhanced NK cell-mediated cytotoxicity." (PMID 35393416, 2022). "We found that, compared to normal tissues, BAX, CHMP2A, CHMPB, IL1A, IL1B, and VPS24 were more strongly expressed in the cytoplasm and nucleus of tumor tissues." (PMID 39744500, 2025). "A key mechanism found was that CHMP2A deletion activated NF-κB signaling and increased secretion of chemokines like CXCL10 and CXCL12, promoting NK cell migration towards tumor cells." (PMID 38891890, 2024). "We observed selective activation of the ESCRT-III effector proteins CHMP2A and CHMP4B in both human and mouse CRC tumor cells." (PMID 38898209, 2024). "Similarly, CHMP3 and CHMP2A show increased expression in HCC tissue samples, thus potentially influencing tumor progression." (PMID 40918134, 2025). "We reason that this could be due to the observed accumulation of aggregated CHMP2A and CHMP4B proteins, members of the ESCRT membrane repair machinery, in the membrane of both human and mouse CRC tumor cells, that were decreased upon ablation of GSDMD in mice." (PMID 38898209, 2024). "Previous literature identified that it has been proposed that CHMP2A, a subunit of endosomal sorting complexes required for transport III (ESCRT-III), may help enhance the effect of NK cells on tumor cells." (PMID 37077542, 2023). "CHMP2A is a subunit of the ESCRT-III protein machinery and involved in EVs secretion, a pathway used by tumor cells to impair NK cells function and therefore a potential target to improve NK cell-mediated antitumor activity, which we wanted to explore more thoroughly." (PMID 35393416, 2022). "Although tumor cells can modulate their sensitivity to NK cells, we did not see any significant change in the expression of NK cell-activating or inhibitory ligands in Cal27 CHMP2A-WT and CHMP2A-KO cells." (PMID 35393416, 2022).
cancer (9 papers, 2014 to 2025). A tumor composed of atypical neoplastic, often pleomorphic cells that invade other tissues. "The results showed that the mRNA expression levels of CHMP2A in cancer tissues were lower than those in normal tissues, and the expression of NLRC4 was just the opposite." (PMID 37077542, 2023). "They found that the deletion of CHMP2A activated NF-κB in cancer cells and increased chemokine secretion, which subsequently promoted the migration of NK cells to cancer cells." (PMID 37427373, 2023). "The data demonstrates that CHMP2A and extracellular vesicles released by tumors can induce programmed cell death in NK cells, thereby diminishing their capacity to efficiently eliminate cancer cells." (PMID 37077542, 2023). "Among the PRGs, CHMP2A and NLRC4 showed the most significant difference in expression between cancer and adjacent cancerous normal tissues." (PMID 37077542, 2023). "CHMP2A and NLRC4 were found to be variables in the prognostic model, and the difference of their expression in cancer and adjacent cancerous normal tissues has been verified in separate cohorts from our hospital." (PMID 37077542, 2023). "Some molecules, such CHMP2A, showed negative associations with the NPS in cancers." (PMID 36170029, 2022).
infection (6 papers, 2013 to 2025). The state of being infected such as from the introduction of a foreign agent such as serum, vaccine, antigenic substance or organism. "By 48 h post-infection, CHMP2A transcripts were ~5-fold higher than in uninfected cells (p < 0.0001)." (PMID 41012666, 2025). "Similarly, at 72 h post-infection, the CHMP2A transcript levels were significantly higher than those of the controls (p < 0.001), but relatively low compared to the 48 h time point." (PMID 41012666, 2025). "Conversely, CHMP2A knockdown impairs autophagic flux in PC12 cells and triggers cell death at levels comparable to those of infection with vectors, suggesting that the underlying mechanism is likely ESCRT-mediated membrane abscission to generate the outer/inner autophagosomal membrane." (PMID 34740380, 2021). "CHMP2A directly interacts with ORF9b of SARS-CoV-2, which was found hyperactively expressed during infection but suppressed by IMD-0354 treatment." (PMID 36093376, 2022).
CHMP2A also shares sentences with these, for which no sentence is quoted: breast carcinoma (4 papers); amyotrophic lateral sclerosis (1); cardiac arrest (1); colorectal cancer (1); Flavivirus Infections (1); frontotemporal dementia (1); ischemic heart disease (1); laryngeal squamous cell carcinoma (1); lymph node metastasis (1); Martsolf syndrome (1); neuroblastoma (1); non-small cell lung carcinoma (1); SARS-CoV Infections (1); Sepsis (1); tongue squamous cell carcinoma (1); triple-negative breast carcinoma (1).